LINC00955 (long independently transcribed non-coding RNA 955)
Synonyms: FLJ35424
Gene: Long non-coding RNA gene on chromosome 4 (3,576,851 to 3,590,995, forward strand). Ensembl gene ENSG00000216560.
Diseases named in the same sentence as LINC00955 in open-access papers:
LINC00955 is named in the same sentence as 2 diseases in open-access papers, as found by Europe PMC text mining. Sharing a sentence is not in itself a finding about the gene and the disease. The quoted sentences say what the papers report.
tumor (1 paper, 2023). "Expression of LINC00955 was markedly lower in CRC tumor tissue than in normal colon tissue." (PMID 37742010, 2023).
LINC00955 also shares sentences with these, for which no sentence is quoted: breast carcinoma (1 paper).